IL6 (interleukin 6)
Diseases named in the same sentence as IL6 in open-access papers (continued):
Sharing a sentence is not in itself a finding about the gene and the disease.
retinal degeneration (21 papers, 2012 to 2025). Degeneration of the retina. "Several cytokines and chemokines including MIP-1α (CCL3), MIP-1β (CCL4), MCP-1 (CCL2), MCP-3 (CCL7), TNF-α, IL-1β and IL-6 have been implicated in photoreceptor-microglial crosstalk and retinal degeneration." (PMID 27814376, 2016). "Another recent study showed that treatment with grape seed extracts was able to reduce the damage of retinal degeneration caused by aging, by attenuating the expression of some pro-inflammatory cytokines [interleukin 6 (IL-6), IL-12 and IL-1β)] or the formation of their messenger RNAs." (PMID 36676026, 2022). "Several lines of evidence suggest that Ccl3, Ccl4, and Il6 are important mediators of pathogenic activity by macrophages in retinal degeneration, which may account for the neuroprotective action of NR58-3.14.3." (PMID 26911327, 2016). "Key inflammatory mediators such as tumor necrosis factor-alpha (TNF-α), interleukins (IL-6, IL-1β), and activated microglia contribute to retinal degeneration." (PMID 40428167, 2025). "P2X7R-mediated IL-6 release was enhanced in RPE cells from the ABCA4−/− mouse model of retinal degeneration." (PMID 33255431, 2020). "As during retinal degeneration, the apoptosis of photoreceptors and glia cell produce a large number of IL-6, which band to gp130, and form a complex to activate the kinase function of JAK2." (PMID 31402855, 2019). "The authors found that IL-33 was released by Müller cells after light exposure, which then induced CCL2, IL-6 and IL-1β expression through autocrine activation of Müller cells and promoted immune cell infiltration and retinal degeneration." (PMID 31796062, 2019). "Müller cells produce protective factors including IL-6 and leptin in response to stress-induced retinal degeneration and regulate photoreceptor protection." (PMID 28767729, 2017). "Our current study demonstrated that retinal degeneration accompanied by upregulation of TNFα and IL-6, GFAP and oxidative damage was ameliorated by blocking TNFα with Infliximab." (PMID 25301432, 2014). "Our finding suggests that the increased number of AF spots is related to resident microglia proliferation, which established a cytokine milieu that was skewed to inflammation by upregulating the expression of the IL-1β, IL-6 and TNFα genes, which subsequently accelerated retinal degeneration." (PMID 23828046, 2013). "Chronic inflammatory mediators such as interleukin-6 (IL-6) and tumor necrosis factor-alpha (TNF-α) further promote retinal degeneration and angiogenesis." (PMID 40507504, 2025). "In summary, these findings position PEDF as a novel agent to downregulate IL-6 production in RPE cells, thereby underscoring its use for the management of retinal degeneration-related inflammation." (PMID 36467689, 2022). "In contrast, low retinal levels of PEDF, such as in retinal degenerations AMD and RP, and dystrophic RPE, would be permissive to inflammatory stimulation by increasing IL-6 and other proinflammatory factors infiltrating in the retina." (PMID 36467689, 2022). "High IL-6 and decreased CNTF levels have been shown to contribute to retinal degeneration and neurodegeneration in DR." (PMID 32116675, 2019). "Furthermore, its anti-inflammatory and antioxidant properties suppress proinflammatory cytokines (e.g., IL-6, TNF-α) and oxidative stress, both of which contribute to retinal degeneration." (PMID 41293731, 2025). "The NaIO3-induced retinal degeneration mock group showed increased expression of Fas, inflammatory cytokines (TNF-α, IL-6, and IL-1β), MCP-1, and macrophages (F4/80), and an elevated M1 (CD11c)/M2 (CD206) macrophage ratio compared with that in the normal mouse group." (PMID 38534392, 2024). "In comparison with normal controls, the mRNA levels of pro-inflammatory cytokines, including IL-1β, IL-6, TNF-α, and MCP-1 increased significantly higher in the MNU group (p < .01; n = 8), indicating that inflammation was involved in the pathogenesis of retina degeneration." (PMID 33501868, 2021).
rosacea (21 papers, 2017 to 2025). A chronic erythematous skin disorder that affects the face. "It was found that rosacea is closely associated with a chronic inflammatory state, particularly with significantly elevated expression of genes such as IL6, OSM, and TNF‐α." (PMID 39823143, 2025). "By reducing IL-6 levels, metronidazole may contribute to a decrease in the oxidative stress response and the associated symptoms of rosacea." (PMID 40006535, 2025). "Metronidazole’s ability to modulate IL-6 in rosacea is likely due to its broader anti-inflammatory and antimicrobial properties." (PMID 40006535, 2025). "TNF-α, IL-6, IL-1α, and IL-1β are well-characterized inflammatory mediators in rosacea pathogenesis, driving key pathological processes including inflammatory cell infiltration, vascular hyperreactivity, and neuroimmune disorder." (PMID 40378103, 2025). "Interleukin-6 (IL-6) is a significant pro-inflammatory cytokine involved in the pathogenesis of rosacea." (PMID 40006535, 2025). "IL-6 contributes to the immune response, inflammation, and angiogenesis, which are key factors in the development and severity of rosacea." (PMID 40006535, 2025). "Elevated levels of IL-6 have been observed in patients with rosacea, indicating its role in the inflammatory processes associated with the condition." (PMID 40006535, 2025). "Meanwhile, EGCG treatment also reduced the expression of pro-inflammatory cytokines, including Il-6, Tlr-2, and Tnf-α in LL-37-induced rosacea-like lesions." (PMID 36937834, 2023). "Tranexamic acid, an antifibrinolytic agent recently used to treat melasma in Asian patients, improves rosacea by reducing IL-6, TNFα, and MMP expression, and also lowers the angiogenesis of rosacea by reducing VEGF expression and the number of CD31+ cells." (PMID 34769465, 2021). "Notably, cytokines such as TNF-α, IL-6, and IL-8 stimulate nociceptors, leading to the burning and stinging sensations commonly experienced by rosacea patients." (PMID 41383625, 2025). "In in vitro experiments, the study found that TLR2 and S100A9 protein levels increased in HaCaT cells under conditions simulating rosacea, and the cytokines IL6, OSM, and TNF‐α were significantly elevated, implying their potential promoting roles in the progression of rosacea." (PMID 39823143, 2025). "Elevated levels of disease characteristic factors, such as KLK5, CAMP, TLR2, and proinflammatory cytokines (such as TNF‐α, IL1β, and IL6), and MMPs have been observed in the skin lesions of human rosacea patients as well as in a mouse model of rosacea induced by LL37." (PMID 39692542, 2024). "The expression of proinflammatory innate cytokines, including Th1 polarizing cytokines Il12b and Tnf; Th17/Th22 polarizing cytokines Il1b, Il23a, and Il6; and Il10 were significantly induced as compared with controls showing a similar expression profile as in rosacea." (PMID 36633910, 2023). "Interestingly, the rosacea patients who expressed higher OPN also expressed higher IL6, IL1B, NLRP3, and TNFa, suggesting that there was a correlation between the expression of OPN and pro-inflammatory factors in rosacea." (PMID 38250077, 2023). "Moreover, studies demonstrated the potential relationship between MLT target genes (MMP9, CCND1, EGFR, ICAM1, PTGS2, and SERPINE1) and rosacea-related key genes (IL-6, IL-1β, IFNγ, IL-17, and TNF-α)." (PMID 34899707, 2021). "Activation of immune-mediated inflammatory pathways appears central to the pathogenesis of rosacea and involves the coordinated activity of several cell types, such as mast cells and macrophages, and the release of proinflammatory mediators, such as IL-6, IL-1β, and TNF-α." (PMID 39247187, 2024). "As for acquired immunity, patients with rosacea are reported to exhibit elevated TNF-α, IFN-γ, and IL-6, which can activate the JAK/STAT pathway." (PMID 39044833, 2024). "IL1B, IL6, NLRP3, and TNFa were important characteristic factors and critical mediators in the inflammation of rosacea." (PMID 38250077, 2023).
rosacea (continued). "Meanwhile, RT-qPCR reflected that rosacea-related pro-inflammatory cytokines increased by LL37 were improved when epidermal TLR7 was silenced, for instance, Tnf-α, Il6 and Il-1β." (PMID 37780385, 2023). "In LL37-induced rosacea-like mice, ART and its derivatives significantly inhibited the expression of pro-inflammatory factors (IL-1β, IL-6, and TNFα) and TLR2." (PMID 35950034, 2022). "The results of RT-qPCR showed that carvedilol alleviated the elevated inflammatory cytokines (TNF-α, IL-6, and IL-8) and macrophage chemotactic factors (ITGAM, ITGB2) of rosacea-like skin, indicating that inflammation and macrophages are inhibited." (PMID 34322115, 2021). "In rosacea patients, the increased levels of IL-6 correlate with ROS production and activation of the hypoxia-induced factor HIF-1α, and both effects are mediated through the IL-6/JAK/STAT3 pathway." (PMID 40006535, 2025). "In addition, RT‐qPCR analysis of inflammatory factors in skin tissue revealed that the expression levels of IL‐6, OSM, and TNF‐α were significantly higher in rosacea patients than in the healthy control group." (PMID 39823143, 2025). "In addition, connective tissue hyperplasia in some rosacea patients is related to the persistence of inflammation, the activation of mast cells and the release of MMP1, MMP9, IL-6, and histamine, and the increased activity of the TRPs14." (PMID 38321132, 2024). "Moreover, MLT repressed the expression of proinflammatory cytokines, such as IL-6, TNF-α, TLR2, TGF-β1, MMP9, and VEGF in rosacea-like dermatitis." (PMID 34899707, 2021). "Pro-inflammatory cytokines such as interleukin (IL)-1 β, IL-6, IL-8, and tumor necrosis factor-α are involved in rosacea pathogenesis, and inflammasome-related genes (CASP-1 and NALP-3) are overexpressed in skin samples from rosacea patients." (PMID 28968402, 2017).
status epilepticus (21 papers, 2011 to 2025). Status epilepticus is defined as a continuous seizure lasting more than 30 min, or two or more seizures without full recovery of consciousness between any of them. "The cerebrospinal fluid (CSF) interleukin-6 (IL-6) level was temporally correlated with the clinical severity of the status epilepticus in our patient, suggesting a causal relationship." (PMID 35820865, 2022). "In animal models of kainic acid (KA)-induced status epilepticus (SE), inflammatory cytokines like interleukin-1 beta (IL-1β), interleukin-6 (IL-6), and tumor necrosis factor alpha (TNF-α) were notably increased in microglia following seizures." (PMID 39684432, 2024). "During hospitalization under the diagnosis of autoimmune encephalitis, status epilepticus developed, and the seizure frequency was temporally correlated with the CSF IL-6 level." (PMID 35820865, 2022). "IL-6 mRNA and IL-6 protein in glial cells was found elevated in animal models of status epilepticus (SE), and the rapid increase of IL-6 expression is associated with membrane depolarizations." (PMID 34832914, 2021). "A study examining patients with autoimmune epilepsy presenting with new-onset refractory status epilepticus found elevated levels of IL-6, TNF-α, IL-2, and IL-4 in the CSF, and elevated levels of IL-6 and TNF-α in the periphery." (PMID 31552027, 2019). "IL-6 is a multifunctional cytokine with pro- but also anti-inflammatory activities, and it has been reported to contribute to neuroprotection after status epilepticus." (PMID 29468563, 2018). "Our patients with intractable epilepsy experiencing status epilepticus attacks also showed high IL-1β, IL-6 and HMGB1 levels." (PMID 21989210, 2011). "The mean IL-6 level of afebrile controls was 34.7 pg/mL, while that of febrile controls was 134.0 pg/mL, and that of afebrile status epilepticus attacks in intractable epilepsy patients was 51.4 pg/mL." (PMID 21989210, 2011). "Furthermore, the interleukin-6 (IL-6) blocker tocilizumab has demonstrated efficacy in treating refractory status epilepticus." (PMID 40144751, 2025). "Overexpression of GPR120 significantly alleviated epileptic activity, reduced neuronal death after status epilepticus (SE), downregulated the expression of IL-1β, IL-6, IL-18, and pyrin domain-containing protein 3 (NLRP3) inflammasome, whereas knockdown GPR120 showed the opposite effect." (PMID 35624482, 2022). "H19 overexpression induced the activation of astrocytes and microglia and the release of proinflammatory cytokines (interleukin-1β and interleukin-6 and tumor necrosis factor-α) in the hippocampus, whereas H19 knockdown inhibited status epilepticus-induced glial cell activation." (PMID 29636074, 2018). "The level of IL-6 in serum and cerebrospinal fluid of patients with status epilepticus is significantly higher than that of patients without status epilepticus, suggesting that seizures may cause further accumulation of IL-6." (PMID 39858450, 2025). "In this study, we investigated the gene expression of proinflammatory cytokines IL-1β (Il1b) and IL-6 (Il6), and anti-inflammatory fractalkine (Cx3cl1) in the hippocampus, entorhinal cortex, and neocortex of rats at different time points after lithium-pilocarpine status epilepticus (SE)." (PMID 37047481, 2023). "The upregulation of both IL6 and IL6R occurs following status epilepticus." (PMID 24146813, 2013).
transient ischemic attack (21 papers, 2010 to 2025). A brief attack (from a few minutes to an hour) of cerebral dysfunction of vascular origin, with no persistent neurological deficit. "The circulating level of IL-6 was significantly associated with corneal nerve fiber loss in patients with transient ischemic attack and acute ischemic stroke." (PMID 36750851, 2023). "A prospective study conducted in 2022 that involved 1,003 stroke patients indicated elevated IL-6 levels were independently linked to a decline in MoCA scores following ischemic stroke and transient ischemic attack (TIA)." (PMID 38414631, 2024). "Continuously injection of recombinant for 7 days IL-6 into the lateral ventricle of gerbils subjected to transient cerebral ischemia, IL-6 injection was found to prevent learning disabilities and delayed neuronal loss." (PMID 35173738, 2022). "Similarly, an increase in interleukin-6 levels was associated with a decline in cognitive functions according to MoCA, assessed between 1 year and 3 months, in patients with AIS or transient ischemic attack (TIA)." (PMID 40305179, 2025). "The IL-6 serum levels changes could also be useful for evaluation of transient ischemic attack (TIA) and silent lacunar infarction." (PMID 31701356, 2020). "At 24 h after transient cerebral ischemia (2 h ischemia/reperfusion), JQ1-treated rats exhibit a marked reduction in neurological deficits, infarct volume, and expression of pro-inflammatory mediators IL-1β, IL-6, IL-17, and TNF-α in the ischemic brain." (PMID 34604312, 2021). "After transient cerebral ischemia injury (1 h ischemia and 3 days of reperfusion), JQ1 significantly reduces infarct volume, neurological deficit score, and glial activation in ischemic mice, along with significantly decreased levels of pro-inflammatory factors IL-1β, IL-6, IL-18, and TNF-α." (PMID 34604312, 2021).
clear cell renal cell carcinoma (20 papers, 2006 to 2025). "Using a FDR of q < 0.05, analyzes revealed that high IL6 expression was associated with higher odds of death for renal clear cell carcinoma (n = 530, HR = 2.49, 95% CI 1.78‐3.49, P < .001), as was high CCL11 (HR = 1.91, 95% CI 1.41‐2.60, P < .001)." (PMID 32383556, 2020). "In renal clear cell carcinoma, NF-κB enhances angiogenesis by elevating pro-angiogenic markers, while its deletion reduces IL-6 and tumor aggressiveness." (PMID 40361374, 2025). "It was reported that CD4+T cells can induce EMT-like features in clear cell renal carcinoma cells by secreting IL-6." (PMID 36186418, 2022). "Recent data for clear cell renal cancer demonstrate that IL6 directly enhances tumor progression and stemness acquisition and allows cells to overcome natural tumor-suppressive mechanisms." (PMID 34638319, 2021). "Although there has been reported lack of correlation between expression of this protein and tumor size or grade our analysis suggests another evidence on regulative role of IL-6 in clear cell renal cell carcinoma." (PMID 31150395, 2019). "Taken together, our findings suggest that the IL6/STAT3 pathway plays a crucial role in the normal fibroblast-enhanced clear-cell renal cell carcinoma metastasis, while GATA3 may mitigate this effect by inhibiting IL6/STAT3 signaling." (PMID 31636361, 2020). "In combination with interleukin 6 (IL-6) secreted by CD4+ T cells, solid stress has also been shown to mediate EMT activation in clear-cell renal cell carcinoma (ccRCC) cells via the Akt/GSK-3β/β-catenin signaling pathway." (PMID 36497097, 2022). "Logistic regression analyzes identified that only IL6 was significantly associated with death within the HNSCC TCGA cohort and OTSCC subgroup, with similar correlation found for increased IL6 expression in the TCGA LSCC and another external cohort of renal clear cell carcinoma." (PMID 32383556, 2020).
coronary artery calcification (20 papers, 2010 to 2025). Calcification of the coronary artery, used as a measure of coronary atherosclerosis, a risk factor for myocardial infarction. "In a recent study, the role of IL-6 was more associated with coronary artery calcification and cardiovascular diseases in ESRD patients." (PMID 35740095, 2022). "Clinical studies demonstrate that elevated serum IL-6 levels in CKD patients correlate with coronary artery calcification (CAC) progression and cardiovascular mortality, with high IL-6 tertiles exhibiting a 2.2-fold increased risk of death." (PMID 40959491, 2025). "Aged garlic extract inhibits progression of coronary artery calcification, lowers IL-6, glucose levels and blood pressure in patients at increased risk of cardiovascular events in a European cohort." (PMID 39108744, 2024). "In CKD children, the Il-6 plasma concentration was significantly elevated and showed a high correlation to the extent of coronary artery calcification." (PMID 35916902, 2022). "Previous studies have proved that in patients with CRF, the levels of serum CRP, IL-6 and other inflammatory factors are positively correlated with the degree of coronary artery calcification." (PMID 34901204, 2021). "Increased GDF-15 correlated with higher TMAO in females only, and with higher coronary artery calcification and IL-6." (PMID 34526107, 2021). "Although inflammatory markers, such as CRP, IL-1β, and IL-6, are associated with cardiovascular diseases, OPG is a unique biomarker in that elevated levels have independently correlated with progression of coronary artery calcification." (PMID 20307322, 2010). "Furthermore, in a recent clinical study measuring IL-6 in patients with coronary artery calcification in CKD, IL-6 was found to be a strong and independent predictor of CV and all-cause death." (PMID 34422725, 2021).